CXCL9 (C-X-C motif chemokine ligand 9)
Diseases named in the same sentence as CXCL9 in open-access papers (continued):
Sharing a sentence is not in itself a finding about the gene and the disease.
tumor (continued). "Further study in mouse model demonstrated that downregulated cGAS-STING pathway led to decreased tumor-infiltrating CD3+ CD8+ T cells by reducing the expression of downstream genes of type I IFN such as chemokine (C-X-C motif) ligands 9 and 10 (CXCL9 and CXCL10)." (PMID 30935414, 2019). "Our findings implied that irradiation induced the release of CCL5, CXCL9, and CXCL11, which may produce a positive chemoattractant gradient in the tumor microenvironment and facilitate the migration of adoptively transferred T cells into tumor tissues." (PMID 31921127, 2019). "Moreover, Th17 can induce production of Th1-related pro-inflammatory cytokines, chemokine (C-X-C motif) ligand 9 and 10 (CXCL9 and CXCL10), at the tumor site." (PMID 30682772, 2019). "However, similar to the present cellular model, chemokines such as CXCL9, CXCL10, CXCL11 secreted in an autocrine manner by tumor cells were considered to contribute to a pro-tumoral microenvironment." (PMID 30847302, 2019). "The results demonstrated that polyphenols induce CXCR3 expression on regulatory T cells and increases CXCR3 ligands (CXCL9, CXCL10, CXCL11) in tumor microenvironment, it may become an important regulator in the treatment of CRC." (PMID 30973890, 2019). "We propose that in extensively infiltrated tumors, TIL-Bs might recruit CD8+ T cells via CXCL9 and due to a highly activated phenotype contribute by secondary costimulation to the maintenance of CD8+ T cells in the tumor microenvironment." (PMID 31623665, 2019). "Interestingly, there was much higher Cxcl9 staining in three of four LLC-sh21 tumors, particularly around the tumor edge compared with LLC-NT tumors." (PMID 31133614, 2019). "TNF-α and IFN-у appear to enhance eosinophilic production of pro-inflammatory Th1-type chemokines such as CXCL9 and CXCL10 whereas TNF-α and IL-4 stimulate eosinophilic production of Th2-type chemokines, which sustain a more immunosuppressive tumor microenvironment." (PMID 31730503, 2019). "In addition, the inflammatory cytokine milieu can also effect T-cell recruitment by altering sensitivity towards selectins, increasing tumor vasculature as evidenced by increased IL-6 production and by inducing T-cell chemoattractants such as CCL5 and CXCL9." (PMID 31747946, 2019). "Inhibition of TIM-3 using an anti-TIM-3 mAb increased the secretion of CXCL9 by the CD103+ DCs, which led to an increased infiltration and activation of CTLs into MMTV-PyMT tumours, thereby improving the therapeutic activity of chemotherapeutic agent paclitaxel." (PMID 31091774, 2019). "For instance, epigenetic reprogramming of genes expressing T helper (TH)-1 chemokines like CXCL9 and CXCL11 might increase CD8+ T cell infiltration into the tumor bed." (PMID 31126321, 2019). "The interaction between CXCL9/CXCL10 with CXCR3 can recruit anti-tumoral dendritic cells, T lymphocytes and natural killer cells to the TME, which could be beneficial for tumor suppression." (PMID 31620367, 2019). "When investigating the plasma concentration of the CXCR3 ligands CXCL9 and CXCL10 in tumor patients treated with anti-PD-1 alone or anti-PD-1 and anti-CTLA-4 antibodies, it was found that the treatment responder group has elevated levels within the first few months after therapy." (PMID 31557787, 2019). "CXCL9 and CXCL10, agonists of the CXCR3, promote the recruitment of CD4+ Th1 lymphocytes, NK cells, and CD8+ cytotoxic T lymphocytes (CTL) to the TME, where they exert a potent anti-tumor activity." (PMID 30319638, 2018). "Moreover, radiation maintains tumor specific molecular immunity and enhances the secretion of tumor cytokines (CXCL9, CXCL10 and CXCL16) to promote tumor immune recognition and T cell infiltration and inducing immunogenic cell death (ICD)." (PMID 29958545, 2018). "The data from this study could suggest that CXCL9 and CXCL10 could play a role in tumor angiogenesis, as down regulation of which on the CVMSCs, have affected MDA-MB231/HUVECs tube formation." (PMID 30458011, 2018).
tumor (continued). "CXCL9 and CXCL12 can form heterocomplexes, and in PCNSL are coexpressed on the tumor vasculature." (PMID 30319638, 2018). "Multiple Th1 cytokines and downstream targets were overexpressed in hot tumours (IFNG, CCL4, CCL5, CXCL9, CXCL10), along with costimulatory and coinhibitory receptors, suggesting these tumours were marked by a state of lymphocyte activation and counter-responses thereto." (PMID 30104673, 2018). "As CXCR3-mediated recruitment appears crucial for T cell entry into tumors and as Treg reduce CXCL9 and CXCL10 expression in tumors, we were eager to determine the source of CXCL10 in tumor tissue, and determine if CXCL10-producing cells were indeed affected by Treg depletion." (PMID 29671006, 2018). "However, when the tumor cells were also stimulated with the type 1 cytokine IFNγ and TNFα an increased expression of CCL2, CCL5, CXCL9, CXCL10 and IL-6 was detected when compared to treatment with the control antibody." (PMID 30192802, 2018). "Stimulation of the cells with 100 ng/ml of the CXCR3 ligands CXCL9 or CXCL10 did not influence tumor cell proliferation." (PMID 28504691, 2017). "Additionally, the expression levels of mRNA for IFN-γ, CXCL9 and CXCL10 were significantly elevated in the tumor tissues." (PMID 28881713, 2017). "In addition, treatment with HMGN1 and R848 increased CTLs in the draining LNs and upregulated chemokines CXCL9 and CXCL10, as well as IFN-γ, all indicators of Th1 immunity in the tumor tissue." (PMID 28881713, 2017). "To test the effects of beta blockers on the chemokine environment in tumors of RRS-exposed animals, we examined the expression of genes that are characteristic of either immune suppression (Foxp3, CCL22) or effector anti-tumor immunity (Granzyme B, CCL5, IFN-γ, CXCL9, CXCL10 and CXCL11)." (PMID 28603578, 2017). "This is consistent with the fact that IFNγ and CXCL9 messenger RNA levels are specifically increased in MT/Shc2F/2F tumours but not in MT/ShcA+/+ or MT/Shc313F/313F tumours." (PMID 28276425, 2017). "Additionally, neoplastic cells coexpressed chemokines (CXCL9, CXCL10, GRO, and CXCL12) and their receptors in both tumours." (PMID 28386296, 2017). "However, their increased efficacy in vivo was also found to be dependent upon secondary overexpression of CXCR3, the main receptor for the IFNγ-dependent chemokine ligands CXCL-9 and CXCL-10 found at elevated levels the TME of inflamed tumours." (PMID 29157300, 2017). "Intratumoral expression of CXCL9 and CXCL10 was significantly reduced in tumors from compound mutant RasApc mice, but not in single transgenic mice expressing oncogenic KRAS, which display lower tumor number and mortality." (PMID 29163806, 2017). "Mechanistic studies showed that upon treatment with TheraVac, Hepa1-6-bearing mice generated increased Hepa1-6-specific CTLs in the draining lymph nodes and showed greatly upregulated expression of CXCL9, CXCL10, and IFN-γ and elevated infiltration of T lymphocytes in tumor tissues." (PMID 28881713, 2017). "In addition, activated macrophages are the cells that secrete most chemokines, including CXCL9 and CXCL10, into the tumor environment." (PMID 28076333, 2017). "Indeed, tumor-homing eosinophils secreted chemoattractants such as CCL5, CXCL9, and CXCL10, which recruited CD8+ T cells to the tumor." (PMID 28791287, 2017). "For example, the tumor supernatants contained low levels of CXCL9, CXCL10 and CXCL11 (data not shown) that bind to CXCR3, a chemokine receptor known to be upregulated on NK cells upon activation and expansion." (PMID 28923105, 2017). "In addition, downregulation of SK1 in B16 led to an increased expression of Th1 cytokines (IL-12, TNFa, IFNg) and chemokines (CCL5, CXCL9, CXCL10) into the tumor." (PMID 27708249, 2016). "CCL-2, 3, 4, and CXCL-9 and 10 were induced in both SUM149 and DU145 tumors; which collectively, may enable the recruitment of immune cells into the tumor." (PMID 27806313, 2016).
tumor (continued). "Also, levels of the three chemokines CXCL9, CXCL10 and CXCL11 were markedly higher, exclusively in Lebanese tumor tissue as compared to non-tumor breast tissue, making BC in this population prone to metastasis." (PMID 27857161, 2016). "These analyses revealed that the tumours are characterized by expression of inflammatory chemokines (CCL2, CCL5, CCL7, CCL8, CCL12, CXCL9, CXCL10 and CX3CL1), reflected by an enrichment of activated Foxp3− and Foxp3+ T cells expressing T helper type 1-associated chemokine receptors." (PMID 25495686, 2015). "This is consistent with the detection of CXCL9 and CXCL10 mRNA in spleens, lymph nodes and tumours." (PMID 25495686, 2015). "Blockade of key factors in IFN-γ/RANTES defense loop including IFN-γ, IP-10/CXCL10, MIG/CXCL9 and RANTES/CCL5 could accelerate tumor formation and progressive dynamics of PMSB-formulated hosts." (PMID 26512920, 2015). "DC-CCL21 mediated anti-tumor responses required IFN-γ, MIG/CXCL9, and IP-10/CXCL10." (PMID 24810425, 2014). "The CD11b+Gr-1int myeloid cells secreted CCL5 and CXCL9 that were important for recruiting NK cells into the tumor microenvironment, demonstrating a role for NLRP3 in the suppression of NK cell activation and promotion of a suppressive tumor environment." (PMID 24273542, 2013). "CXCL9 was highly expressed in the cytoplasm of tumor cells, but was nearly absent from the tumor infiltrating lymphocytes." (PMID 24278236, 2013). "Five mouse-specific cytokines were significantly (P=0.03) higher expressed in VEGFA165 tumours compared with control tumours: interleukin 5 (IL5), IL7, chemokine (C-X-C motif) ligand 9 (CXCL9, MIG), colony-stimulating factor 1 (macrophage) (MCSF) and interferonγ (IFNG)." (PMID 22045186, 2011). "Tumor samples of IL-13Rα2 DNA and ECDα2 boost vaccine-treated mice collected were positive for CXCL9, whereas control tumor samples were negative for this chemokine." (PMID 21067607, 2010). "As for the murine cells, the chemotactic responses towards various concentrations of chemokines were tested and confirmed the migratory ability of the human tumour cells in response to two of the three ligands (CXCL9, CXCL10 but not CXCL11)." (PMID 19436305, 2009). "In murine studies, CCL21-DC induced tumor regression, stimulated production of IFN-γ and the CXC chemokines MIG (CXCL9) and IP-10 (CXCL10) at the tumor site, and decreased local concentrations of immunosuppressive inflammatory mediators including IL-10, PGE2, and TGF-β." (PMID 18644162, 2008). "Both CXCL9/MIG and CXCL10/IP-10 are chemotactic for stimulated CXCR3-expressing T lymphocytes that could further amplify IFN-γ at the tumour site." (PMID 16598185, 2006). "The induction of CXCL9/CXCL9/MIG and CXCL10/CXCL10/IP-10 may be responsible in part for the tumour reduction following CCL19 administration." (PMID 16598185, 2006). "Notably, CXCL9, CXCL10, and CXCL11 utilize the shared receptor CXCR3 and engage in similar mechanisms that facilitate the recruitment of T cells and other immune cells to the tumor microenvironment, contributing to antitumor responsiveness." (PMID 40909948, 2025). "Thus, the role of CXCL9/CXCR3 in HCC is complex, suggesting that its therapeutic potential may depend on the specific tumor context or setting." (PMID 40145607, 2025). "The chemokines CCL2 and CCL5 well known attractants of CTLs as well as CXCL9 and CXCL10 powerful chemoattractant of activated CTLs were all highly induced by mIL12 mRNA treatment in both models and likely laid the ground for trafficking and retention of these effectors deep within the tumor cores." (PMID 40560386, 2025). "Building upon prior research suggesting that chemokines like C-X-C motif chemokine ligand 9 (CXCL9) and C-X-C motif chemokine ligand 10 (CXCL10) recruit CAR-NK cells, we hypothesized that tumor cell m6A methylation, regulated by Methyltransferase-like 3 (METTL3), influences chemokine secretion." (PMID 39497707, 2025).
tumor (continued). "Additionally, the upregulation of chemokine genes such as CXCL9 and CXCL10 may facilitate T cell migration to the tumor microenvironment, further strengthening their immune surveillance capabilities." (PMID 40534857, 2025). "We also observed that tumor cells that engaged senescence-related transcriptional programs, or “Sen-High” cells, upregulated IFN-γ signaling machinery, including Ifngr1, Ifngr2, Jak1, Jak2, Irf1, and Stat1, as well as IFN-γ target genes Cxcl9, Cxcl10, and Tap1." (PMID 40299790, 2025). "Bridging chemotherapy is often used to control tumor progression during this period and has been shown to enhance CAR-T efficacy by reducing immune suppressor cells in the tumor microenvironment and upregulating chemokines such as CCL5, CXCL9, and CXCL10 to improve T cell trafficking." (PMID 40312353, 2025). "However, IL-6 and CXCL9, baseline concentrations did not significantly differ by patient age group when evaluating within the same tumor type (P > 0.05)." (PMID 40258833, 2025). "Simultaneously, IFN-γ induces the expression of chemokine ligands such as CXCL9 and CXCL10, which bind to the CXCR3 receptor on effector T cells and NK cells, promoting their robust infiltration into the tumor microenvironment and effectively suppressing tumor growth." (PMID 41359111, 2025). "Thus, potential interactions between Il12b cDC1s and stem‐like TCF1+ CD8+ T cells, as well as Cxcl9 cDC1s and effector TCF1− CD8+ T cells, might be important for anti‐tumour immunity across species." (PMID 40745918, 2025). "However, even in HGSOC itself, this distinguishes CX3CL1 from other T-cell recruiting chemokines such as CXCL9 and CXCL10, which can combat tumour growth in vivo by enhancing lymphocyte infiltration and represent a strong and robust protective prognostic marker." (PMID 39862711, 2025). "The chemokines CCL2 and CCL5 well known attractants of CTLs as well as CXCL9 and CXCL10 powerful chemoattractants of activated CTLs were all highly induced by mIL12 mRNA treatment in both models and likely laid the ground for trafficking and retention of these effectors deep within the tumor cores." (PMID 40321762, 2025). "CXCL9 enhances immune surveillance and promotes the killing of tumor cells, while the negative correlation between APOB and CXCL9 may imply a potential role of APOB in tumor immune evasion." (PMID 40696350, 2025). "A CXCR3/CXCL9/CXCL10 axis could drive T cell infiltration into KPCY55 tumors of GPR55 KO mice, suggesting that GPR55 suppresses this pathway in PDAC, thereby promoting tumor growth." (PMID 39885986, 2024). "In addition, analysis using the TISIDB database to determine correlations with various chemokines showed that STX4 also had a positive correlation with CXCL9 and CXCL10, which contribute to a "hot" tumor microenvironment and can increase immunotherapy effectiveness." (PMID 38226288, 2024). "In addition, MWA combined with αPD-L1 treatment promoted the production of CXCL9 and blocked IFN-γ/CXCL9/CD8+ T axis which could promote tumor progression." (PMID 39372416, 2024). "Using isolated tumor tissue, we analyzed gene expression related to cytotoxicity (Perforin, Granzyme B, Granulysin, and FasL), inflammatory or chemotactic cytokines (IFN-γ, CXCL9, CXCL10, and CXCL11), and CD8+ T cell activation and proliferation (CD69, Tbx21, IL-2, and IL-12b)." (PMID 39066478, 2024). "The related mechanisms may involve an inhibitory effect on the IL-6/LIF system, promoting the release of ligands of the CXCR3 receptor, chemokines CXCL9 and CXCL10 (IP-9), which chemoattract several types of immune cells that infiltrate a tumor and prevent its growth." (PMID 38891915, 2024).
tumor (continued). "In addition, the recruitment of cDC1 within tumors has other benefits, including the production of chemokines CXCL9 and CXCL10 to recruit CXCR3 effector T cells for tumor infiltration, and a further enhancement of the antitumor activity of T cells and NKs by cytokine IL-12." (PMID 38339158, 2024). "Moreover, activators of FAO, like bezafibrate, could potentiate anti-PD-1 therapy by inducing the expression of CXCL9 and CXCL10 from tumor cells and CXCR3 on intra-tumor effector T cells." (PMID 39119332, 2024). "Indeed, the link between CXCR3 ligands, including both CXCL9 and CXCL10 in promoting anti-tumour immunity is becoming increasingly recognised, with their expression correlating with improved patient responses and sensitisation to immune checkpoint blockade in pan-cancer studies." (PMID 39165364, 2024). "CXCL9 and CXCL10 are well known IFN-γ-inducible chemokines produced by endothelial cells, monocytes/macrophages and fibroblasts in the tumor microenvironment and prevent tumor angiogenesis by blocking endothelial cell proliferation, inducing tumor necrosis 32-35." (PMID 39629126, 2024). "Furthermore, the coexpression of the CCL2 receptor CCR2b or CXCL9 in CAR-T cells can enhance the infiltration and tumor killing ability of CAR-T cells, which can lead to improved tumor control and potentially enhance the efficacy of synergistic therapies involving radiotherapy and immunotherapy." (PMID 39578426, 2024). "In our cohort, samples containing more CD8+ T cells, ≥ 10 cells per mm2, in the tumor parenchyma contained more CXCL9+ and CXCL10+ tumor cells, indicating that tumor cell expression of these key chemokines may also drive tumor parenchymal infiltration of CD8+ T cells." (PMID 38822345, 2024). "Combined inhibition of EZH2 and DNMT1 augmented the expression of the inflammatory chemokines CXCL9 and CXCL10, which increased TILs and decreased tumor progression, thus improving the therapeutic efficacy of PD-L1 checkpoint blockade and adoptive T-cell transfusion in tumor-bearing mice." (PMID 37198402, 2023). "However, a number of tumor types, including prostate cancer, did not express CXCL9 and CXCL10, which prevented CD8+ effector T cells from activating." (PMID 37546397, 2023). "In addition, we investigated whether the expression of angiogenic factors, such as vascular endothelial growth factor (VEGF), was suppressed in CXCL9- and CXCL11-expressing tumor tissues using IHC." (PMID 37218983, 2023). "Therefore, we speculated that NE regulates the secretion of CXCL9 and ADO in tumour cells through the WNT7A/β-catenin signalling pathway." (PMID 36646807, 2023). "By contrast, expression of EZH2 in cancer cells may dampen anti-tumor immunity and hinder the infiltration of the tumor by effector T cells through EZH2- and DNMT1-mediated epigenetic silencing of TH1-type chemokines (i.e., CXCL9 and CXCL10)." (PMID 36627707, 2023). "Also, the WNT pathway activation would cause decreased expression of CXCL9 and CXCL10, making CTLs not being able to recruit to the tumor region." (PMID 37546397, 2023). "CXCL9 expression detected in the peripheral blood may not be representative of the tumor parenchyma." (PMID 37644593, 2023). "Furthermore, “helped” cDC1 upregulate CXCL9/10/11 that may promote attraction of CXCR3+ effector T-cells into the TME, as shown for tumor-infiltrating cDC149,50." (PMID 36639382, 2023). "We showed that increased levels of NE in LUAD patients could decrease the secretion of chemokine CXCL9 and disturb the immunosuppressive metabolite ADO in tumour cells, thereby reducing the proportion and function of CD8+ T cells in the tumour microenvironment, resulting in anti-PD-1 mAb resistance." (PMID 36646807, 2023).